FGF10 (fibroblast growth factor 10)
Diseases named in the same sentence as FGF10 in open-access papers (continued):
Sharing a sentence is not in itself a finding about the gene and the disease.
pulmonary fibrosis (16 papers, 2012 to 2023). Chronic progressive interstitial lung disorder characterized by the replacement of the lung tissue by connective tissue, leading to progressive dyspnea, respiratory failure, or right heart failure. "For example, FGF10, the nearest gene to rs116351545, has been implicated in various lung diseases such as idiopathic pulmonary fibrosis, bronchopulmonary dysplasia, and chronic obstructive pulmonary disease and lung function." (PMID 37488738, 2023). "For example, FGF10 levels were reduced in the lungs of aged mice before and after the injury and in idiopathic pulmonary fibrosis patients with the progressive disease compared with stable disease." (PMID 34383782, 2021). "FGF10-FGFR2b signaling has been shown to promote the resolution of pulmonary fibrosis via a number of mechanisms, including the one we mentioned earlier in this review." (PMID 34124037, 2021). "On the other hand, overexpression of Fgf10 reduces the severity of lung fibrosis in bleomycin-induced mice." (PMID 34055804, 2021). "FGF10 dysregulation in human has been implicated in some major respiratory diseases, such as bronchopulmonary dysplasia (BPD), Idiopathic pulmonary fibrosis (IPF) and chronic obstructive pulmonary disease (COPD)." (PMID 34055804, 2021). "For example, fibroblast growth factor-10 was markedly suppressed in the subjects with progressive idiopathic pulmonary fibrosis, and both TGF-β1 and SHH signaling were identified as critical mediators of this effect in MSCs." (PMID 31952198, 2020). "The role of FGF10 in cerebral ischemia injury, pulmonary fibrosis and wound healing, has been extensively researched." (PMID 30532765, 2018). "Recently we have further shown that FGF10 signaling, a process that is necessary for distal lung morphogenesis, can also antagonize bleomycin-induced lung fibrosis in adult mice by a mechanism involving inhibition of active TGF beta ligand bioavailability." (PMID 23259863, 2012). "As a crucial mesenchymal–epithelial signaling growth factor in embryonic development, tissue repair, and regeneration, the role of FGF10 has been investigated in several disease conditions such as cerebral ischemia injury, pulmonary fibrosis, and wound healing." (PMID 32116715, 2020). "FGF10 expression in the lungs of idiopathic pulmonary fibrosis (IPF) vs. donors as well as progressive vs. stable IPF patients supports our conclusion that FGF10 deficiency could be causative for IPF progression." (PMID 30487814, 2018). "We have also recently shown that FGF10 signaling, a process that is necessary for distal lung morphogenesis, can also antagonize bleomycin-induced lung fibrosis in adult mice, by a mechanism involving inhibition of active TGF beta ligand bioavailability and hence less tissue inflammation." (PMID 23259863, 2012). "We found that overexpression of Fgf10 or treatment of recombinant FGF10 (rFGF10) significantly improved the degree of pulmonary fibrosis in bleomycin-injured mice, whether administered simultaneously or at day or day 14 after injury, by promoting the active proliferation of IAAPs." (PMID 37166489, 2023). "To determine the effect of exogenous FGF10 on fibrosis formation, we validated in our experimental conditions in the widely used bleomycin (BLM) model of lung fibrosis." (PMID 35954241, 2022). "In murine bleomycin-induced lung fibrosis, inactivation of the FGF10/FGFR2B axis led to increased honeycombing lesions, while FGF10 overexpression enhanced fibrosis resolution, further deciphering the complex network of signaling pathways that operate in IPF." (PMID 34248677, 2021). "In the rodent bleomycin-model, enhanced Fgfr2b-signaling on alveolar epithelial cells via the exogenous application or induction of FGF10 or FGF7, conferred increased survival and reduced lung fibrosis." (PMID 26138239, 2015).
pulmonary fibrosis (continued). "In a bleomycin-induced mouse model of lung fibrosis [a model for idiopathic pulmonary fibrosis (IPF)], alveolar epithelial Fgf10 overexpression using transgenic mice significantly increased the infiltration of Cd4PosCd25PosFoxp3Pos T regulatory cells during the inflammation phase." (PMID 34136479, 2021). "In another study on FGFR antagonists, inhibition of endogenous FGFR2b ligands (FGF7 and FGF10) does not alter bleomycin-induced pulmonary fibrosis, suggesting that these ligands are not essential for fibrosis." (PMID 34383782, 2021). "Fgf10-expressing MYFs dedifferentiate back into LIFs but do not downregulate their Fgf10 expression levels during the resolution phase of lung fibrosis suggesting that they retain a memory of the injury which might protect against further injury." (PMID 30319693, 2018).
chronic obstructive pulmonary disease (13 papers, 2013 to 2023). A chronic and progressive lung disorder characterized by the loss of elasticity of the bronchial tree and the air sacs, destruction of the air sacs wall, thickening of the bronchial wall, and mucous accumulation in the bronchial tree. "For example, studies on the human lung suggest that narrower airway lumens, which are also associated with genetic variants in the fibroblast growth factor 10 (FGF10) gene, are a susceptibility factor for chronic obstructive pulmonary disease." (PMID 37085733, 2023). "For example, the absence of the right medial-basal airway is associated with a type of chronic obstructive pulmonary diseases and two types of SNPs are found within the same intron of Fgf10 in those cohorts." (PMID 33057360, 2020). "Fibroblast growth factor 10 haploinsufficiency in human is associated with chronic obstructive pulmonary disease (COPD)." (PMID 30487814, 2018). "Furthermore, FGF10 haploinsufficiency has been shown to be associated with chronic obstructive pulmonary disease (COPD)." (PMID 25298902, 2014). "In this connection, it was recently demonstrated that genetic variants affecting the FGF10 signaling pathway were important determinants of adult lung function that may ultimately contribute to chronic obstructive pulmonary disease." (PMID 24004862, 2013). "List of single nucleotide variants identified in FGF10 associated with the risk of nonsyndromic cleft lip with or without cleft palate, chronic obstructive pulmonary disease and myopia." (PMID 36124135, 2022).
bronchopulmonary dysplasia (12 papers, 2017 to 2023). Bronchopulmonary dysplasia is a chronic respiratory disease that results from complications related to lung injury during the treatment of infant acute respiratory distress syndrome in low-birth-weight premature infants or from abnormal lung development in older infants. "Inflammation-induced FGF10 protein deficiency is associated with bronchopulmonary dysplasia (BPD), a chronic lung disease of prematurely born infants characterized by arrested alveolar development." (PMID 28516419, 2017). "As a result, inhibition of miR-421 reduced bronchopulmonary dysplasia in mice by upregulating Fgf10." (PMID 32796770, 2020). "Here we review the cellular and molecular mechanisms linking FGF10 to multiple lung diseases, from bronchopulmonary dysplasia in extremely preterm neonates, cystic fibrosis in children, and chronic adult lung disorders." (PMID 30429870, 2018). "FGF-10 also reduced in the lung tissue of infants with bronchopulmonary dysplasia." (PMID 29732364, 2018). "Interestingly, decrease in FGF10 expression in the lungs is also observed in human patients displaying bronchopulmonary dysplasia (BPD)." (PMID 33195211, 2020). "Whereas FGF10 mutations alone may not be sufficient to cause severe human lung malformations or congenital lung disease, alterations in FGF10 expression have been described in bronchopulmonary dysplasia (BPD)." (PMID 30930931, 2019).
pancreatic cancer (12 papers, 2008 to 2025). "FGF10 is also implicated in pancreatic cancer, and that overexpression of FGFR2b is associated with metastatic invasion." (PMID 30425728, 2018). "In this study, we investigated the molecular mechanisms underlying the aggressiveness of pancreatic cancer, and found that FGF10/FGFR2-IIIb-signalling plays an important role in inducing migration and invasion of pancreatic cancer cells." (PMID 18594526, 2008). "Similarly, FGF10 has been associated with tumorigenesis and progression in lung and pancreatic cancers." (PMID 39833941, 2025). "However, it is unknown if FGF10/FGFR2-IIIb-signalling is associated with carcinogenesis in pancreatic cancer." (PMID 18594526, 2008). "Herein, we summarize the recent information about the involvement of FGF10 in pancreas development and diseases with a focus on pancreatic cancer." (PMID 30425728, 2018). "In pancreatic cancer, FGF10 is found in stromal cells, close to the tumor cells, and is thought to interact with FGFR2-IIIb on the tumor cells, thereby inducing cell migration and invasion." (PMID 21767389, 2011). "In conclusion, our results indicate an important role for the interaction between stromal cells and parenchymal cells mediated by FGF10/FGFR2-IIIb signalling in pancreatic cancer." (PMID 18594526, 2008). "Our results show that FGF10 is expressed in stromal cells scattered around pancreatic cancer cells, suggesting a possible interaction with cancer cells expressing FGFR2-IIIb." (PMID 18594526, 2008). "Overall, the results show that FGFR2 is expressed in pancreatic cancer tissue, and that its ligand, FGF10, is expressed in stromal cells." (PMID 18594526, 2008). "This suggests that FGF10/FGFR2 signalling is a promising target for new molecular therapy against pancreatic cancer." (PMID 18594526, 2008). "To examine the expression pattern of FGFR2 and FGF10 in pancreatic cancer tissues, we performed immunohistochemical staining of 76 tissue samples of invasive pancreatic ductal carcinoma and of normal pancreatic tissues." (PMID 18594526, 2008). "We are trying to examine if the proteinase activity of MT1-MMP is increased by FGF10 stimulation in pancreatic cancer cells." (PMID 18594526, 2008). "FGF‐10 had differentially expressed in response to gemcitabine and erlotinib, suggesting that FGF‐10 could be a predictive biomarker for chemotherapeutic treatment response in pancreatic cancer patients." (PMID 30945363, 2019). "FGF‐10 was observed in stromal cells surrounding the cancer cells in pancreatic cancer tissues." (PMID 30945363, 2019). "A thorough understanding of FGF10 signaling machinery and its crosstalk with other pathways in development and pathological states may provide novel opportunities for pancreatic cancer targeted therapy and regenerative medicine." (PMID 30425728, 2018). "Previously it was demonstrated that FGF10 induces cell migration and invasion in pancreatic cancer." (PMID 24002438, 2013). "A member of the fibroblast growth factor FGF10 has also been reported in several cancer studies; multiple lines of evidences show that FGF10 plays important roles in various cancer types, including prostate and pancreatic cancers." (PMID 21569311, 2011). "According to these data, we hypothesize that FGF10 is expressed in T cells surrounding pancreatic cancer cells." (PMID 18594526, 2008). "In this study, we show that FGF10/FGFR2-signalling has an important role in pancreatic cancer progression, and we suggest that these results may lead to a new therapy and a better prognosis for patients with pancreatic cancer." (PMID 18594526, 2008). "As a result, cancer cells acquire metastatic properties, suggesting that FGF10/FGFR2-IIIb-signalling may promote migration of pancreatic cancer cells through induction of TGF-β1 expression." (PMID 18594526, 2008). "To examine this hypothesis, we analysed the effects of FGF10 on the proliferation, invasion and migration of pancreatic cancer cells." (PMID 18594526, 2008).
pancreatic cancer (continued). "To understand how FGF10/FGFR2-IIIb signalling induces cell migration and invasion of pancreatic cancer cells, we examined whether FGF10 influences the expression of genes related to cell mobility." (PMID 18594526, 2008). "Next, we examined whether FGF10 affects migration or invasion of pancreatic cancer cells." (PMID 18594526, 2008). "The expression pattern of FGF10 and FGFR2 in cancerous tissue and the poor prognosis of patients with high FGFR2 expression in cancer cells indicate that a stromal cell–epithelial cell interaction through FGF10/FGFR2 signalling might induce the malignant properties of pancreatic cancer." (PMID 18594526, 2008). "FGF10 induces migration and invasion in pancreatic cancer cells through interaction with FGFR2, resulting in a poor prognosis, thus FGF10/FGFR2 signaling is a promising target for new molecular therapy against pancreatic cancer." (PMID 31607941, 2019). "Fibroblast growth factor 10 induced cell migration and invasion of CFPAC-1 and AsPC-1 pancreatic cancer cells through interaction with FGFR2-IIIb, a specific isoform of FGFR2." (PMID 18594526, 2008). "Immunostaining of pancreatic cancer tissues showed that FGFR2 was expressed in cancer cells, whereas FGF10 was expressed in stromal cells surrounding the cancer cells." (PMID 18594526, 2008). "This suggests that FGF10 and FGFR2-IIIb are promising candidates as target molecules for new therapy against pancreatic cancer, and that therapeutic agents directed against these molecules may improve the prognosis of patients with this disease." (PMID 18594526, 2008). "Pancreatic cancer cells did not express FGF10 in any samples, but scattered cells in stroma surrounding the cancer cells showed strong expression of FGF10 (arrows)." (PMID 18594526, 2008). "Reverse transcriptase–PCR analysis showed that all four cell lines did not express FGF10 mRNA, consistent with the results of immunostaining showing FGF10 expression in stromal cells, but not in cancer cells, in pancreatic cancer tissue." (PMID 18594526, 2008). "In pancreatic cancer tissues, cancer cells expressed FGFR2 at various levels, but did not express FGF10." (PMID 18594526, 2008).
prostate carcinoma (11 papers, 2006 to 2025). A carcinoma that arises from epithelial cells of the prostate gland. "Paracrine FGF10 signaling to prostate cancer cells causes increased AR expression and activated AKT." (PMID 36671452, 2022). "AR expression has also been detected in prostate cancer-associated fibroblasts (CAFs) in vitro and siRNA-mediated depletion of AR from these stromal cells resulted in a decrease in FGF10 expression." (PMID 30405704, 2018). "For prostate cancer organoid cultivation, A83-01, FGF10, FGF2, prostaglandin E2(PGE2), Nicotinamide and p38 inhibitor SB202190, N-acetylcysteine, B27 and Rho kinase inhibitor Y-27632 were added into the general organoid culture medium." (PMID 37576596, 2023). "Bmi-1 inhibition protects prostate cells from FGF-10-driven hyperplasia and slows the growth of prostate cancer." (PMID 33584271, 2020). "Recent in vivo studies have provided further evidence for a role of a FGF10/FGFR/Src signaling axis in prostate cancer." (PMID 30405704, 2018). "Almost all members of FGFs are up-regulated in human prostate cancer, including FGF2, FGF7, FGF10 and FGF1741." (PMID 32139705, 2020). "Particularly, inhibition of BMI1 protects prostate cells from FGF10-induced hyperplasia and reduces the growth of aggressive PTEN-deletion-induced prostate cancer." (PMID 31366128, 2019). "Following host castration, a subset of FGF10-induced prostate adenocarcinoma cells showed continued survival and proliferation, suggesting that paracrine FGF10 stimulation may contribute to the development of androgen independence in this murine model of prostate cancer." (PMID 30405704, 2018). "Given that Perlecan has been shown to modulate the signaling of multiple growth factors including FGF2, FGF10 and VEGF, we asked if the reduction of prostate cancer cell growth in Perlecan siRNA treated cells was a result of decreased SHH signaling." (PMID 16507112, 2006). "However, for mice prostate cancer organoids, FGF10, FGF2, PGE2, Nicotinamide and SB202190 were not necessary." (PMID 37576596, 2023).
idiopathic pulmonary fibrosis (10 papers, 2018 to 2023). Idiopathic pulmonary fibrosis (IPF) is a nonneoplastic pulmonary disease that is characterized by the formation of scar tissue within the lungs in the absence of any known cause. "Recent studies have suggested that deficiencies in FGF10 can be a key driver for chronic lung diseases, such as chronic obstructive pulmonary disease, bronchopulmonary dysplasia, and idiopathic pulmonary fibrosis (IPF)." (PMID 31958320, 2020).
lung diseases (10 papers, 2016 to 2023). "Recent papers have reported that mutations and single nucleotide polymorphisms (SNPs) in the Fgf10 gene are correlated with human lung disease." (PMID 33057360, 2020). "Importantly, FGF10 signaling is dysregulated in various human lung diseases including COPD, as heterozygous loss-of-function mutations in FGF10 causes COPD in human." (PMID 36183124, 2022). "FGF10 plays an important role as a fibroblast growth factor in lung development and lung diseases, but its protective effect against acute lung injury is unclear." (PMID 36618911, 2022). "Because of its important roles in structural morphogenesis, epithelial differentiation, and protection from injury, FGF10 is an intriguing target for preventing and treating lung disease." (PMID 30429870, 2018). "As a driver of lung airway branching morphogenesis, FGF10 signaling defects during development lead to neonatal lung disease." (PMID 30429870, 2018). "Understanding the connections between FGF10 and lung diseases may lead to exciting new therapeutic strategies." (PMID 30429870, 2018). "Our study focused on human subjects with progressive (vs. stable) fibrotic lung disease, supporting a role for FGF-10 in disease progression rather than disease initiation or susceptibility." (PMID 27869174, 2016). "However, the role of BMP4 in lung diseases and the regulatory effect of FGF10 on BMP4 are not fully understood." (PMID 36618911, 2022).